ESR1 (estrogen receptor 1)
Diseases named in the same sentence as ESR1 in open-access papers (continued):
Sharing a sentence is not in itself a finding about the gene and the disease.
tumor (continued). "Over-representation of transcription DNA-dependent and cell cycle-related genes and transcripts directly or indirectly regulated by ER was detected in genes differentially expressed in ESR1-positive BRCA1 tumours." (PMID 19826428, 2009). "Detailed examination of the profiles of apparently uniform classes revealed molecular differences within both the ESR1-positive and ESR1-negative tumours." (PMID 19826428, 2009). "Two transcription factors of this family present in our array, NFκB2 and RELB, showed over-expression in ESR1-negative BRCA1 tumours with fold changes relative to ESR1-positive tumours ranging from 3.7 to 4.1, respectively (two-tailed t-test P-values <0.05." (PMID 19826428, 2009). "CpG island methylation of both WIF1 and ESR1 genes made a significant contribution to the distinction between the normal mucosa of cancer patients and that of neoplasia-free patients." (PMID 18542073, 2008). "The level of methylation was significantly lower in normal-appearing cancer mucosa compared with neoplasia-free mucosa for ESR1, MINT31 and WIF1." (PMID 18542073, 2008). "Microarray analysis of primary tumours shows that the Polycomb-group gene BMI1 is overexpressed in ERα-positive tumours (r = 0.62 for ESR1 versus BMI1, p = 4 × 10-7; similar results were obtained in several other microarray data sets)." (PMID 17573968, 2007). "The localization of AKT1 and ESR1 in tumor cells, alongside SRC and IL6 in myeloid cells, highlights potential mechanisms through which the decoction impacts tumor-immune interactions, potentially altering immune surveillance and tumor progression in high-risk locally advanced NPC." (PMID 40746726, 2025). "Moreover, HCC patients with lower ESR1 expression levels had a significantly worse prognosis than those with higher levels, which supported the tumor suppressor function of ESR1." (PMID 41306771, 2025). "The downregulation of p-PI3K and p-AKT confirms suppression of survival signaling, while the inhibition of key oncogenic regulators AKT1, MTOR, HIF1A, SRC, and ESR1 suggests broader effects on tumor metabolism, hypoxia adaptation, and growth factor receptor pathways." (PMID 40746726, 2025). "The general objective of this study was to evaluate the frequency and clinical value of the ESR1 and PIK3CA mutations identified in cfDNA and to compare these results with primary tumor samples to evaluate if the mutation was originally present in the tumor or if it occurred during metastasis." (PMID 40076662, 2025). "This hypothesis may be supported by the circulating tumor DNA biomarker analysis from the MONARCH-3 trial, which found a lower incidence of ESR1 mutations under abemaciclib intervention." (PMID 40740245, 2025). "No additional next-generation sequencing or broad genomic profiling was conducted on the tumor; this is a limitation of our report, as such analysis might have identified actionable mutations (for example, PIK3CA or ESR1 mutations) to further guide therapy." (PMID 40548112, 2025). "The importance of ESR1 mutations in mBC development has not been discovered until 2013, when genomic sequencing of circulating tumor cells (CTC) in patients with metastatic disease allowed for its identification as a key factor of ET resistance." (PMID 40989687, 2025). "Notably, GATA3 correlates with hormone receptor (ER/PR) positivity (both 90% in our case), implicating estrogen-response pathways (e.g., ESR1/GREB1) in tumor biology." (PMID 40969274, 2025). "This suggests that its targets, such as SH3BP5, NBEA, ZBTB20, ESR2, and ESR1, may escape miR-204-mediated repression, potentially leading to their overexpression, which could promote tumor growth and metastasis." (PMID 41009685, 2025).
tumor (continued). "However, analysis of the patient’s circulating tumor DNA revealed an alteration in estrogen receptor 1 (ESR1) and the progression of her disease despite therapy, which prompted the initiation of palliative treatment with elacestrant." (PMID 39925600, 2025). "Additionally, in vitro findings require validation in vivo to assess E2/ESR1 effects on tumor progression." (PMID 40342082, 2025). "ESR1 mutations appear primarily during progression, as no mutations were found in primary tumor samples." (PMID 40076662, 2025). "Cord blood from newborns (WBCs) DNA methylation of the ACSL3 promoter, Intragenic p19INK4α DNA methylation in adult blood (PBLs), CDH1, HIN1, PARPβ, and TWIST promoter DNA methylation in adult tumor tissue DNA methylation of the ESR1 promoter, BRCA1, CCND2, and DAPK." (PMID 40182693, 2025). "In addition, there was a correlation between ESR1 mRNA levels and MKI67 expression, which is associated with tumor cellular proliferation." (PMID 40666735, 2025). "The luminal B tumours exhibit the highest ESR1 and lowest ESR2 expression among all subtypes, with ESR2 being particularly scarce—a feature that distinguishes luminal B from ERα-negative cancers, where ESR2 may have clinical relevance." (PMID 41007296, 2025). "Suppresses ESR1 fusion‐driven tumor growth in preclinical models." (PMID 41329030, 2025). "A gain-of-function mutation within the FGFR3 gene in a transgenic mouse model facilitated the development of low-grade papillary bladder cancer, while ESR1 expression was significantly down-regulated, suggesting the involvement of ERα in urothelial tumorigenesis as a tumor suppressor." (PMID 40486871, 2025). "No patient was found to have a mutation in ESR1 in the primary tumor sample, while ~12% were identified with PIK3CA mutations." (PMID 40076662, 2025). "When combined with abemaciclib (a CDK4/6 inhibitor), alpelisib (a PI3K inhibitor), or everolimus (a mTOR inhibitor), imlunestrant demonstrates enhanced anti-tumor efficacy, including against brain metastases, irrespective of ESR1-mutation status." (PMID 40641933, 2025). "Additionally, in the overall study population, there was an approximate 20% relative reduction in the risk of disease progression or death, which was a favourable benefit for patients with ESR1 m tumours." (PMID 40275985, 2025). "Our results suggest that assessing AR/ESR1 expression ratios could help predict tumor response and support the use of AR antagonists in cases with elevated ratios." (PMID 40593140, 2025). "Integrative analyses highlighted ESR1 overexpression in tumors with relapse, showing that this biomarker may discriminate tumor groups according to recurrence status with high accuracy." (PMID 40367016, 2025). "Previous studies have demonstrated that ESR1 exerts hepatoprotective effects during liver carcinogenesis by delaying hepatocyte apoptosis, ameliorating hepatic fibrosis, and inhibiting tumor growth via ESR1-mediated signaling, thereby reducing HCC susceptibility." (PMID 40630198, 2025). "In fact, the analysis of ESR1 mutations through liquid biopsy, by measuring circulating tumor DNA (ctDNA), has gained clinical relevance as a non-invasive approach to molecularly monitor patients with metastatic breast cancer (mBC) [6,]." (PMID 41142848, 2025). "Reduced ESR1 mRNA expression in total RNA may result from either a lower proportion of ER‐positive tumor cells or decreased ER expression within the ER‐positive tumor cell population." (PMID 40666735, 2025). "Overexpression of ESR1 slightly affected stemness and malignant potential in ECSCs, and the addition of 2 nM E2 markedly decreased stemness and inhibited malignant behaviours of ECSCs, including proliferation, invasion and tumour formation, in soft agar." (PMID 40342082, 2025).
tumor (continued). "Lastly, we identified a region in an ESR1 intron that has three binding sites for the transcriptional insulator CCCTC‐binding factor (CTCF) where CpG methylation is strongly negatively correlated with ER expression in both tumours and cell lines." (PMID 39108022, 2025). "The GIST-enhanced gene expression of ESR1 (t test, P = 0.036) improved tumor cell detection." (PMID 39830364, 2025). "Through the examination of the relationship between DNA methylation and RNA expression, we discovered a clear correlation between the methylation of CG sites in the promoters of GPER1 and ESR1 and their respective RNA expression in around one-third of tumor types." (PMID 38666956, 2024). "Activating estrogen receptor mutations (ESR1 mutations) are acquired through prior aromatase inhibitor therapy for ABC, with circulating tumor DNA analysis demonstrating that the mutations are present in 15% to 40% of patients treated with prior aromatase inhibition." (PMID 37982575, 2024). "The mediator target gene ESR1 is highly expressed in the tumor." (PMID 38254989, 2024). "The results of genome-wide expression analysis confirmed that ESR1 was negatively correlated with tumor size and disease stage in HCC, suggesting that the loss of ESR1 could accelerate the development of cancer." (PMID 39544939, 2024). "In contrast to ESR1 mutations, which are mostly acquired following prior endocrine treatment, PIK3CA mutations are found at similar frequencies in primary and metastatic breast tumors, and are generally considered an early event related to tumor initiation." (PMID 38605020, 2024). "Clinical benefit was observed regardless of baseline ESR1 mutation status as determined by circulating tumor DNA sequencing." (PMID 38800404, 2024). "The association between ESR1 and S100A8 and S100A9 expression levels was positive in Basal patients but negative in Her2, Luminal A, and Luminal B. S100P and S100A14 expression levels were higher in tumor tissues than in normal ones." (PMID 39594999, 2024). "In addition, in the current era of CDK4/6 inhibitors, the activity of fulvestrant on ER-positive breast cancer (both the wild-type ESR1 and the ESR1 mutant) after tumor progression on CDK4/6 inhibitors appears limited." (PMID 38339371, 2024). "We have found 2 vascular phenotypes based on the high/low ESR1 tumor expression." (PMID 38411438, 2024). "Altogether, these results confirm that Esr1 (ERα) was expressed in both the stromal and epithelial/tumor components of the prostate, and that, importantly, estrogens induced a metabolic gene signature in the epithelial/tumor compartment." (PMID 38625747, 2024). "We also found mutation only in the tumor tissue in the genes DICER, ESR1, KIT, PDGFRA, and RAF1." (PMID 38565739, 2024). "Overall, these results demonstrated that the well‐established markers (i.e., ESR1, PGR, and MKI67) showed distinct spatial distributions and that the cells included in PNP spots (i.e., ESR1+ and/or MKI67+ cells) were potentially associated with oestrogen‐mediated tumour growth." (PMID 38282415, 2024). "Alternative splicing may also alter protein localization, as has been reported for some ESR1 (ERα) isoforms, thus creating further tumor-specific targets." (PMID 39095991, 2024). "Significant associations were observed between tumor survival and ESR1 methylation (159 records, 68 negative and 91 positive), ESR2 methylation (46 records, 27 negative and 19 positive), and GPER1 methylation (67 records, 35 negative and 32 positive)." (PMID 38666956, 2024). "ESR1 has been identified as a tumor suppressor gene that can predict tumor progression." (PMID 39544939, 2024). "In addition, principal component analysis (PCA) shows clear separation between PRs ESR1LOW and tumours expressing high ESR1 (GRs and PRs ESR1HIGH)." (PMID 37419892, 2023).
tumor (continued). "In a mouse model, functional ESR1 was shown to be necessary for PCa development, and during the progression of PCa, ESR1 was found at low levels in the prostatic epithelium but was overexpressed in the stroma, promoting tumor progression in a paracrine manner." (PMID 37965470, 2023). "According to the results of other studies and our study, it may be speculated that the enhanced ESR1 expression in GC patients with a dismal outcome is due to the reaction of enhanced tumor size." (PMID 37037466, 2023). "While ESR1 mutations are a well-established mechanism of resistance to ET, it is less clear if specific types of ETs, such as AI plus/minus LHRHa or TAM plus/minus LHRHa, are more likely to cause the selection of tumor clones bearing ESR1 gene mutations." (PMID 36595552, 2023). "We found that DNAm AA was positively associated with ESR1 and PGR gene expression in both tumor and normal tissue samples, suggesting that the activation of estrogen signaling pathway may accelerate breast tissue aging." (PMID 36991516, 2023). "We also decided to retain ESR1 and ERBB2, since their mutation prevalence increased gradually from primary tumor to extracerebral metastases and brain metastases, an observation that may have therapeutic implications." (PMID 36980614, 2023). "We show that ESR1 amplifications and MAP3K mutations are selected during ETs employing estrogen deprivation, and that MAP3K alterations are associated with higher risk of tumor relapse and worse patient overall survival." (PMID 36595552, 2023). "In addition, the following pathway correlation analysis found that EGFR and ESR1 were positive correlated with tumor cell apoptosis, which further supported our conclusion." (PMID 37542141, 2023). "Groups L3 and L4 cells derived from the tumor zone and had low expressions of ESR1/PGR/HER2." (PMID 37644609, 2023). "Indeed, the ESR1 gene promoter was found to be extensively methylated in PCa cell lines and tissues, with a positive correlation between methylation levels and tumor pathological grade." (PMID 37760622, 2023). "Another study indicated that ESR1 may be a potential pharmacological target for CRC treatment as ESR1 may serve as a tumor-regulated gene via methylation regulation." (PMID 37155147, 2023). "Patients whose tumor or ctDNA tests remain ESR1 wild-type may warrant retesting at subsequent progression to monitor the rise of ESR1 mutations." (PMID 37958343, 2023). "EGFR and ESR1 are confirmed as tumor drivers and drug targeting factors in ccRCC." (PMID 37542141, 2023). "It is clear from the EMERALD trial that patients with a tumor harboring ESR1 mutation benefitted more from elacestrant vs those without the mutation." (PMID 36229710, 2022). "One of the primary characterized mechanisms of acquired resistance to endocrine therapy is the acquisition of mutations within the ligand-binding domain (LBD) of the estrogen receptor alpha gene (ESR1) activating the receptor constitutively thereby rendering tumor cells less dependent on estrogen." (PMID 35151276, 2022). "Patients detected with increased circulating ESR1 mutation without tumor progression were randomized to remain on current therapy or to switch to fulvestrant (known to be more effective in the presence of ESR1 mutation) in combination with palbociclib." (PMID 36077738, 2022). "MCF-7 cells harboring ESR1 mutations supported robust tumor growth, while the corresponding cells harboring WT ESR1 failed to generate viable tumors." (PMID 35881485, 2022). "Similarly to ESR1 mutation assessed with ctDNA, testing for PIK3CA mutations in ctDNA is concordant with the testing of tumor tissue and the prediction of alpelisib efficacy." (PMID 36077738, 2022).
tumor (continued). "In conclusion, this study provides important new insights into the biology of triple negative PABC and suggests that several copy number alterations, particularly 8p loss, TOP2A loss, ESR1 loss and CCNE1 gain are implicated in tumor progression during pregnancy." (PMID 35792986, 2022). "Our data also suggest that transcription factors such as CREB1 and ESR1 as well as pioneer factors such as PU.1 and Sp1 may contribute to the differentiation of MDSCs in the tumor." (PMID 36480485, 2022). "In addition, our ESR1 mutant detection rate should be interpreted with caution, considering that we only used tumor samples from subjects with relapse." (PMID 35501333, 2022). "However, when LM slices were compared to myometrial slices, upregulation of ESR1 mRNA (10-fold, p < 0.0001) was observed in tumor cells." (PMID 35884847, 2022). "The tumor suppressive effects of estrogens were originally thought to be facilitated by estrogen receptors ERα and ERβ, but recent research from our lab has identified a third ER, G-protein Estrogen Receptor 1 (GPER1), that plays a critical role in suppressing PCa growth." (PMID 35018219, 2022). "Obtaining circulating DNA from liquid biopsies conserves the genomic landscape of the tumor suggesting that this less invasive detection methods may efficiently identify ESR1 fusions, particularly in metastatic ET resistant ER+ breast cancer." (PMID 36686845, 2022). "We note that the evaluation of the tumor’s ESR1 methylation status in cfDNA may be confounded by the presence of a background age-related methylation signal of ESR1 in WBCs." (PMID 35628441, 2022). "Regarding CNAs, the main affected genes in this series of primary MN that recurred are located on chromosomes 22q (TIMP3), 1p (TP73), 6q (ESR1 and PARK2), and 18q (BCL2); the association among these chromosomes’ alterations and tumor recurrence has been previously demonstrated." (PMID 36011000, 2022). "In addition, estrogen receptor alpha (ESR1)-mediated stimulation of proliferation of the epithelial cells contributes to conversion of DNA damage into mutations (i.e., tumor initiation) as well as tumor promotion and progression." (PMID 34921608, 2022). "The results showed that ESR1 mutations were only detected in metastatic foci, but not in primary tumor tissue samples." (PMID 35549970, 2022). "Analyses of matched primary and metastatic samples or serial plasma samples may elucidate how rare ESR1-mutant clones arise in primary tumors and become metastatic through dissemination in the bloodstream, in accordance with clinical tumor progression." (PMID 35501333, 2022). "Resistance to endocrine therapy can develop due to mutation or loss of endocrine receptors on tumor cells (e.g., hormone receptor-negative and ESR1 gene mutations) or via the upregulation of pathways independent of endocrine receptors altogether." (PMID 35505937, 2022). "Thus, future study with larger tumour representation is warranted to test LATS inhibitors for ERα dependent cancers, particularly those harbouring hormone therapy resistant ESR1 mutations." (PMID 35217640, 2022). "The total concordance rate between ESR1 status on tumor tissue and plasma was 91%." (PMID 33777770, 2021). "The level of mRNA expression of ERBB2 and ESR1 was evaluated in 799 tumor samples." (PMID 34198891, 2021). "The effect of ESR1 on these processes is compatible with the literature on the impact of ESR1 in other cancers, with impact on transcriptional regulation, cell cycle, and tumor suppression." (PMID 34881186, 2021).